PIR (pirin)
Diseases named in the same sentence as PIR in open-access papers (continued):
Sharing a sentence is not in itself a finding about the gene and the disease.
tumor (continued). "Although PIR is widely expressed in normal and tumour tissues, its function is poorly known." (PMID 29118270, 2017). "The ability of G-MDSCs to retain stemness diminished when silencing piR-823 in MM cells, which reduced tumor growth and angiogenesis in vivo, implying that piR-823 might be a unique anti-cancer therapy that targets both G-MDSCs and CSCs in the MM microenvironment." (PMID 39102033, 2025). "Furthermore, we have also investigated whether this PIR-TCR can inhibit PDX-derived tumor cells proliferation by Incucyte live-cell analysis system (Sartorius, Essen Bioscience)." (PMID 37377887, 2023). "The results showed that piR-1742 could significantly delay tumor proliferation." (PMID 37332045, 2023). "Hence, AC092115.3 may affect the inhibitory effect of Treg cells on tumor immunity by regulating NF-κB transcriptional activity of specific target genes mediated by PIR." (PMID 34880875, 2021). "However, SAPS2 itself does not have an apparent relevance to tumorigenesis and thus the tumor-suppressive effect of piR-8041 is likely mediated by the targeting of other unknown sequences of imperfect complementarity." (PMID 30701019, 2018). "The results demonstrated that in the piR‐RCC overexpression group, tumor metastasis was inhibited, highlighting the direct effect of piR‐RCC on RCC metastasis." (PMID 40411401, 2025). "Expression of serum EV-derived piRNAs iselevated in HCC patients, and some of them (e.g., piR-15254, piR-1029,novel-piR-35395, novel-piR-32132, and novel-piR-43597) are potentially usablein HCC diagnosis even in patients with a low tumor burden." (PMID 40771849, 2025). "To confirm this proposal, we performed xenograft tumor formation assays with HCT116 cells and found that PIR KD dramatically retarded tumor formation and upregulated FAS expression accordingly." (PMID 38148593, 2024). "In this research, the MUC12 expression level was shown to be elevated in larger xenograft tumor samples, whereas the expression of MUC12 was inhibited when piR-1742 was knocked down." (PMID 37332045, 2023). "One of the first degree interactors of Pirin is PPP2CA, which is a serine/threonine phosphatase with activities critical for maintaining healthy cellular functions and suppressing tumor." (PMID 38033031, 2023). "PiR-168112 was also downregulated in the PDAC and IPMN samples compared to tumour cell lines (Log2 fold change = –26.81; adjusted p-value = 1.31 × 10−15)." (PMID 36555927, 2022). "piR-020619 and piR-020450 are observed to be increased even in early stages of CRC with a small sized tumor." (PMID 34193172, 2021). "In prostate cancer, piR-001773 and piR-017184 synergistically regulate the transcription of protocadherin 9 (PCDH9) under homeostasis and thereby promote tumor invasion and metastasis." (PMID 34118972, 2021). "This is the first study to identify a novel piRNA, piR-hsa-211106, which plays a critical role in LUAD as a tumor-suppressor RNA, and we further elucidated the novel regulatory mechanism underlying by which piRNAs regulate cancer." (PMID 34249688, 2021). "The tumor promoter RASSF1C up-regulates piR-34871 and piR-52200 and down-regulates piR-35127 and piR-46545 through the RASSF1C-PIWIL1-piRNA axis to promoted LC stem cell proliferation, colony formation, and EMT." (PMID 31399034, 2019). "Together, these findings establish piR-hsa-8393202 and piR-hsa-8429916 as stable, tumor-derived circulating piRNAs that exert pro-oncogenic effects in LUAD, promoting tumor cell proliferation and survival while maintaining excellent molecular stability suitable for clinical biomarker application." (PMID 41319254, 2025).
tumor (continued). "Notably, conditioned media from LUAD cells contained significantly higher levels of piR-hsa-8393202 and piR-hsa-8429916 compared to BEAS-2B cell supernatants, indicating active secretion by tumor cells." (PMID 41319254, 2025). "While T cells transduced with the TCR from beads stimulated T-iPSC did not express 4-1BB nor produced IFNγ, those with the TCR from tumor cell-stimulated T-iPSC expressed 4-1BB and produced IFNγ as PIR-TCR." (PMID 37377887, 2023). "piR-2158 showed downregulation in primary tumors compared to the matching adjacent non-malignant tissues, which was independent of the tumor subtypes." (PMID 37153732, 2023). "Five piRNAs (piR-hsa-1849, piR-hsa-5938, piR-hsa-9491, piR-hsa-12487, and piR-hsa-12488) selected based on NGS data as the five most significantly dysregulated piRNAs in GBMs were validated on an independent cohort of 77 GBM samples and 23 non-tumor controls." (PMID 34485142, 2021). "Although the difference of the PIR expression was not statistically significant between tumor and normal tissues, AD event in PIR was significantly upregulated in ICC." (PMID 34760694, 2021). "RT-qPCR analysis of confirmed decreased expression of piR-38756, piR-57125, and piR-30924 in non-metastatic primary tumours compared to normal tissue." (PMID 26768585, 2016). "In the current study, expression of PIR in tumor tissues was virtually similar to the non-cancerous tissues." (PMID 23374458, 2013). "For example, piR-25783 activates the TGF-β/Smad2/Smad3 pathway in fibroblasts by increasing Smad2 and Smad3 phosphorylation, promoting the fibroblast-to-myofibroblast transition (FMT) process and enhancing the proliferative and metastatic properties of tumor cells." (PMID 38915084, 2024). "Thus, piR-162725 seems an optimal candidate biomarker to differentiate between tumour and non-tumour samples." (PMID 36555927, 2022). "Interestingly, piRNAs from the same region [piR-26681 (DQ596465), piR-26683 (DQ596467), piR-26685 (DQ596469), piR-26686 (DQ596470)] are found to be downregulated in GBM, which may suggest a potential tumor suppressive role of this genomic region." (PMID 34485142, 2021). "Results indicated that pirin was not overexpressed in HPV-positive tumours." (PMID 29118270, 2017). "The discordant results detected between mRNA and protein expression of FAAH, PIR and TAF5L, could be due to multiple factors including, tumor heterogeneity, posttranscriptional regulation, differences in mRNA and protein turnover rates or poor specificity of the antibody used for IHC." (PMID 23374458, 2013). "Additionally, piR‐RCC overexpression plasmid expressed GFP fluorescence, and immunofluorescence and H&E staining of tissue sections from the left kidney of the RCCM@NPs‐treated group indicated the predominant accumulation of the nanomedicine in the tumor tissue." (PMID 40411401, 2025). "Moreover, we observed reduced expression of Ki‐67 (a tumor proliferation marker) and STAT3 in piR‐RCC overexpression or stattic treatment groups alone compared to the control group, with even lower expression in piR‐RCC overexpression and stattic combination treatment group." (PMID 40411401, 2025).
cancer (50 papers, 2013 to 2026). A tumor composed of atypical neoplastic, often pleomorphic cells that invade other tissues. "In this study, we explored the expression and oncogenic role of piR-823 in OC tissue samples and its association with epigenetic regulation, cancer stemness, and EMT." (PMID 41596471, 2026). "Exploring the association between ncRNAs-SNPS, and more precisely, piR-823 SNPs, and the cancer mechanism(s), is important to investigate to link certain polymorphisms to changes in cancer incidence, progression, or remission in the future." (PMID 39102033, 2025). "Pirin is involved in various cellular activities and has been implicated in tumorigenesis and malignancy of various cancers." (PMID 39917624, 2025). "For instance, a substantial decrease in the expression of piR‐823 within cancer tissues has been linked to enhanced disease‐free survival rates." (PMID 40737301, 2025). "This increased DNA damage is linked to increased cytoplasmic translocation and extracellular release of high mobility group box 1 (HMGB1) in PIR-deficient cancer cells." (PMID 39534872, 2024). "The most enriched KEGG pathways and DisGeNET analyzed diseases for interactors of Pirin are associated with cancers." (PMID 38033031, 2023). "Recent studies demonstrated possible involvement of aberrant piRNAs expression in tumorigenesis and all the hallmarks of cancer, and thereby suggested as a diagnostic and prognostic marker (e.g., piR-L-163, piR-823)." (PMID 35755302, 2022). "Whereas piR-30924 and piR-38756 are associated with cancer metastasis, showing higher expression in metastatic and decreased expression in non-metastatic tumors compared to normal tissue." (PMID 31399034, 2019). "Serum levels of piR-823 are considered a diagnostic biomarker in several cancers." (PMID 41596471, 2026). "Among these genes, aberrant expression of PIR enhanced cancer aggressiveness, suggesting that PIR might be a promising diagnostic marker for HSPC and CRPC." (PMID 30444038, 2019). "Several other chemical inhibitors of pirin have also been identified with effects on cancer cell function." (PMID 39677728, 2024). "The exact mechanism of how interaction with these proteins contribute to Pirin mediated metastasis of cancer cells is yet to be known, but Pirin signaling appears to play a key role in cancer invasiveness and migration." (PMID 38033031, 2023). "Subsequently, we screened out piR-hsa-164586 using high-throughput sequencing and then verified its expression level in cancer patients and healthy individuals by qPCR." (PMID 36249068, 2022). "Recent investigations have been carried out on the contribution of Pirin in various types of cancer, including epithelial tumors as well as those from the hematopoietic and neurological systems." (PMID 33557375, 2021). "Pirin protein, a cupin superfamily member with a suggested role in cancer, is of particular interest." (PMID 33557375, 2021). "This suggests a key participation of Pirin in cancer promotion and progression, although additional experimental approaches, including animal models, for testing Pirin-mediated tumorigenesis are warranted." (PMID 33557375, 2021). "Recent findings have shown that Pirin plays a role in the development of cancer in epithelial lung, skin, cervical, and oral tumors." (PMID 33557375, 2021). "Here we summarize the biological functions of Pirin in relation to its role in cancer, suggesting that Pirin is a potential therapeutic target." (PMID 33557375, 2021). "To decrypt underlying molecular mechanisms by which piR-39980 modulates chemosensitivity of HT1080 cells, we predicted its target genes that relate to chemoresistance and cancer progression." (PMID 34799689, 2021). "Functional analysis on the downstream related genes, e.g. PIR for the ACE2-PIR fusion, revealed their association with apoptosis, cancer suppression and metastasis, etc.." (PMID 32982583, 2020).
cancer (continued). "the translated protein, Pirin, harbors an Fe+2-binding site functioning as an OS sensor in NF-κB activation and cancer progression, whose overexpression is mediated by factors promoting OS." (PMID 32679705, 2020). "Loss‐of‐function assays using siRNA or an inhibitor (bisamide) showed that downregulation of PIR expression blocked cancer cell migration and invasion." (PMID 30444038, 2019). "piR-651 levels are also associated with TNM stages, with low differentiated cancers associated with elevated piR-651." (PMID 31399034, 2019). "In PCa, PIR was reported to enhance cancer cell proliferation by negatively regulating apoptosis induced by EAF2/U19." (PMID 30444038, 2019). "Our present data showed that siRNA‐mediated PIR knockdown significantly inhibited cancer cell aggressiveness." (PMID 30444038, 2019). "Our results revealed that 3 piRNAs (piR-23,619, piR-24,000 and piR-1245) were up-regulated, while piR-26,525 was down-regulated in cancer tissues (with ≥ 2 fold change and a P value ≤ 0.01)." (PMID 29382334, 2018). "Collectively, our analyses provided evidence that expression ofpiR-1245 is not only upregulated, but also associates with specific clinicopathological features, suggesting that piR-1245plays a crucial role in the cancer pathogenesis within the colon." (PMID 29382334, 2018). "Consistent with this paradigm, our gene expression profiling results revealed that piR-1245 affects cancer-related pathways and functions as an oncogenic regulator." (PMID 29382334, 2018). "Unfortunately, we only found piR-1245 and piR-26,525 had significant differential expression between cancer and normal tissues." (PMID 29382334, 2018). "Knocking down of piR-34871 and piR-52200 expression resulted in reduced cell proliferation of normal lung and breast epithelial cells cancer cells." (PMID 28423657, 2017). "Expression levels of those piRNAs were comparable in SF and in different cancer cell lines; piR-16735 was the most expressed piRNA, followed by piR-4153, piR-823 and the least expressed piR-16659." (PMID 27893851, 2016). "In the same study, it was argued that silencing of the gene site piR-Hep1 prevented the cancer cells from proliferating, migrating, and attacking the healthy tissue." (PMID 27414029, 2016). "In our study, the piRNA site is thought to be the one that plays a role in piR-651 cancer development." (PMID 27414029, 2016). "ALDH1A1 (network 1), and PIR (the most differentially expressed protein) were selected for further validation based on involvement in IPA network, regulation level and known cancer association." (PMID 26317550, 2015). "The PIR functions as a transcriptional regulator whose expression is deregulated in several cancer types." (PMID 23374458, 2013). "Thus, a key proposed function of pirin on p65 NFκB signaling appears not to be correct and further studies will be required to fully understand pirin’s mechanisms in cancer and other mammalian cell functions." (PMID 39677728, 2024). "The recent work on the role of pirin to suppress apoptosis and ferroptosis may represent another key contributor to the actions of pirin inhibitors in cancer." (PMID 39677728, 2024). "Furthermore, the upregulation of piRNA-823 and piR-016658 and the downregulation of piR-016975 have been observed to promote cancer cell stemness." (PMID 39795985, 2024). "Following above clues, we investigated in depth the molecular mechanism underlying PIR inhibition of cancer cell apoptosis and found that NFκB2 rather than NFκB1 is involved in PIR regulation of apoptosis by establishing the PIR‐NIK‐NFκB2‐FAS regulatory axis." (PMID 38148593, 2024). "Earlier reports also suggest a role Pirin in different cancers." (PMID 38033031, 2023). "The potential role of Pirin regulated pathways in cancer progression and/or metastasis may be elucidated by analysis of its interaction with other proteins and associated biological processes." (PMID 38033031, 2023).
cancer (continued). "This recently discovered activity of piR-1742 in RCC cells might serve as an inspiration for future research into the functions of additional piRNAs in other kinds of human cancers." (PMID 37332045, 2023). "The Pirin protein is a member of the cupin superfamily proposed to play a role in cancer." (PMID 37308689, 2023). "piR-30188/PIWIL3 binds to OIP5-AS1, a cancer-associated lncRNA, a target of miR-367-3p in gliomas." (PMID 37568728, 2023). "The restoration of piR-823 in GC cells inhibits cancer cell growth both in vitro and in vivo." (PMID 37568728, 2023). "The expression and/or function of piR-021285 in other types of cancer have yet to be determined." (PMID 34295823, 2021). "In view of the crucial function of Wnt signaling in regulating stem cell-like properties in cancer, we attempted to determine whether piR-823 had any effect on Wnt signaling." (PMID 33791297, 2021). "Finally, we propose a model in which Pirin is upregulated by physical, chemical or biological factors involved in OS and cancer development." (PMID 33557375, 2021). "Furthermore, we have also found that upregulated expression of piR-hsa-211106 imparts a synergistic anti-cancer effect with chemotherapeutic agents on LUAD cells." (PMID 34249688, 2021). "The levels of piR-5937 and piR-28876, in particular, were able to differentiate between cancer patients and healthy donors with high sensitivity and specificity, and after chemotherapy treatment, the expression levels were again comparable between cases and controls." (PMID 31416190, 2019). "Previous reports suggested that PIR contributes to malignant transformation of cancer cells by acting as a transcriptional cofactor that interacts with the Bcl3–NF‐қB complex in several cancers." (PMID 30444038, 2019). "Overexpression of piR-36,712 led to accumulation of cancer cells in G0/G1 phase suggesting a cell cycle arrest; however, knockdown of piR-36,712 significantly decreased the number of cancer cells in G0/G1 phase but increased the number of cancer cells in G2 phase." (PMID 30636640, 2019). "Similarly, the heightened expression levels of piR‐32051, piR‐39894, and piR‐43607 have been identified as being significantly correlated with the metastasis of ccRCC, as well as with advanced clinical staging and poor cancer‐specific survival." (PMID 40737301, 2025). "In addition to cancer cells, the dependence on Nrf2 for the expression of pirin was also observed in normal human lung fibroblast IMR90 cells, where treatment with TBE-31 or sulforaphane caused similar levels of induction (by ~2.5-fold) of the expression of pirin." (PMID 35204145, 2022). "Moreover, the miR‐455‐5p/PIR axis contributed to cancer cell aggressiveness." (PMID 30444038, 2019). "In BC, piR-823 upregulated DNMTs expression levels, promoted DNA methylation of the adenomatous polyposis coli (APC) gene, activated Wnt signaling, and induced cancer cell stemness in luminal subtype cells." (PMID 41596471, 2026). "Through this axis, overexpressed PIR inhibits NFκB2 transcriptional activity toward FAS and therefore assists cancer cells surviving from FAS‐dependent insults, especially from immune defense system." (PMID 38148593, 2024). "Pirin also interacts with cytoplasmic protein NCK1, which mediates cancer metastasis as well as functions as an intracellular messenger leading to angiogenesis in the ERBB signaling pathway (KEGG entry: hsa04012)." (PMID 38033031, 2023). "First, the sample size was small, particularly for verifying the expression of piR-hsa-164586 in NSCLC and other cancers, so it is necessary to verify piRNAs of extracellular vesicles in a larger population." (PMID 36249068, 2022). "Here, we report the identification of piR-hsa-211106 that is significantly downregulated in LUAD tissues compared with normal tissues and acts as a possible cancer suppressor." (PMID 34249688, 2021).